IGF1 (insulin like growth factor 1)
Diseases named in the same sentence as IGF1 in open-access papers (continued):
Sharing a sentence is not in itself a finding about the gene and the disease.
B cell deficiency (1 paper, 2021). A broad classification of disorders where circulating numbers of B lymphocytes are decreased or ineffective. "B-cell deficiency did not affect expression of IL1β nor other DAM genes, such as TNFα, Igf1, and Lilrb4." (PMID 33846335, 2021).
bacterial meningitis (1 paper, 2025). Inflammation of the membranes surrounding the brain and spinal cord due to a bacterial infection. "Furthermore, patients with bacterial meningitis are at a higher risk than those with other CNS infections for developing neuropsychiatric and endocrinologic complications both in the short and long term, and they also exhibit the lowest plasma IGF-1 levels among the groups studied." (PMID 39787566, 2025).
Batten disease (1 paper, 2007). "Insulin-like growth factor-1 (IGF-1, upregulated about 3-fold) has been noted to increase in concentration in the cerebrospinal fluid of patients with infantile Batten disease, and has been used to delay interneuron loss in the mnd model of Batten disease." (PMID 18021406, 2007).
bile duct cancer (1 paper, 2020). "Both in vitro and in vivo researches have proved that up-regulation of IGF-1 contributed to the proliferation of bile duct cancer cells and the inhibition of apoptosis." (PMID 32709224, 2020).
blood pressure (1 paper, 2019). "Consistent with previous studies, our investigation indicated that the 12-weeks PCA administration elicited the decreases in high blood pressure together with restoring vascular function by improving endothelium-dependent vasorelaxation induced by insulin and IGF-1 in aging SHR." (PMID 30934575, 2019).
bone osteosarcoma (1 paper, 2020). A usually aggressive malignant bone-forming mesenchymal neoplasm arising from the bone. "Studies of IGF1 isoforms expression on other human bone osteosarcoma cells (U2OS) showed the lowest overall production of IGF1, with Eb as predominant isoform compared to other cell lines (HepG2, HeLa, K562)." (PMID 32977489, 2020).
Brachycephaly (1 paper, 2019). An abnormality of skull shape characterized by a decreased anterior-posterior diameter. "Conceivably, a combination of variants promoting brachycephaly (e.g. Smoc2), on a background of those promoting growth (Igf-1) may place the Boxer at extreme risk of premature ageing and brain tumours." (PMID 31467332, 2019).
Cerebellar atrophy (1 paper, 2022). Cerebellar atrophy is defined as a cerebellum with initially normal structures, in a posterior fossa with normal size, which displays enlarged fissures (interfolial spaces) in comparison to the foliae secondary to loss of tissue. "The results of the present study revealed that the IGF-1 treatment restored motor function, reduced neuronal cell death, and effectively prevented cerebellar atrophy in the SCA3 84Q transgenic mice." (PMID 35203722, 2022).
cerebral malaria (1 paper, 2024). A sequestration of Plasmodium falciparum in the brain, which can cause coma and/or seizures. "It suppresses inflammatory mediators like TNF-α in the central nervous system, thereby administration of IGF-1 reduces cerebral malaria induced mortality in mice." (PMID 39492784, 2024). "Mice with non-cerebral malaria, express high level of IGF-1." (PMID 39492784, 2024).
chlamydial infection (1 paper, 2012). "This was confirmed by the reduction of plasma insulin like growth factor-1 at high chlamydial infection intensity (P<10−4)." (PMID 23024776, 2012). "Again, IGF-1 completely followed the pattern of body weight gains and plasma albumin, and the reverse patterns of chlamydial infection intensity, conjunctival inflammation, and plasma globulin." (PMID 23024776, 2012). "Comparison of the clusters unambiguously showed that high chlamydial infection intensity highly significantly co-segregated with high plasma globulin and low albumin, IGF-1, and body weight gain." (PMID 23024776, 2012). "To further confirm the central role of the liver in chronic inflammation-mediated growth depression, and to address the collinearity of age, chlamydial infection and weight gains, we analyzed plasma insulin-like growth factor-1." (PMID 23024776, 2012). "Again, plasma IGF-1 was highly significantly decreased at high chlamydial infection and closely tracked growth rates, confirming that C. pecorum infection reduced growth rates of calves via an infection intensity-dependent liver response to Chlamydia-induced systemic inflammation." (PMID 23024776, 2012).
chorioamnionitis (1 paper, 2023). A morphologic finding indicating inflammation of the fetal sac membranes. "It is postulated that with the progression of acute histologic chorioamnionitis, there is a decrease in the level of the intact form of insulin-like growth factor binding protein 1, ultimately affecting IGF-1 bioavailability." (PMID 36911032, 2023).
chronic asthma (1 paper, 2013). An asthma that is characterized by the development of persistent airway inflammation and recurrent attacks of breathlessness and wheezing, which vary in severity and frequency. "The evidence of increased expression of Igf1 is consistent with our earlier published evidence in a related animal model of chronic asthma, in which upregulation of Igf1, Fgf1 and Tgfb1 mRNA was demonstrated in the airway epithelium." (PMID 23611895, 2013).
Co-infection (1 paper, 2017). "We observed a small but significant attenuation in IGF-1 decline in HIV/HCV co-infection compared to mono-infection." (PMID 28503671, 2017).
cocaine addiction (1 paper, 2015). "Further research is necessary to elucidate the role of BDNF and IGF-1 in the transition to cocaine addiction and associated psychiatric comorbidity." (PMID 25734326, 2015). "Although our findings support the importance of monitoring BDNF and IGF-1 in the context of cocaine addiction with psychiatric comorbidity, we are aware of the limitations of the present exploratory study." (PMID 25734326, 2015). "In summary, BDNF, IGF-1 and IGFBP-3 were not affected by a history of pathological use of cocaine supported by the absence of associations with other molecules sensitive to cocaine addiction." (PMID 25734326, 2015). "We cannot conclude whether these changes in BDNF and IGF-1 concentrations are exclusive to cocaine addiction or not because new studies in psychiatric patients with no history of drug use will be necessary to elucidate their role in mental disorders." (PMID 25734326, 2015). "Focusing on cocaine addiction, we observed no changes in the plasma concentrations of IGF-1 and IGFBP-3 of abstinent users and concentrations did not correlated with addiction-related variables such as severity cocaine symptom, abstinence or duration of cocaine use." (PMID 25734326, 2015).
cognitive (1 paper, 2021). "Increased hippocampal oxidative stress, reduced hippocampal mitochondrial OXPHOS coupling efficiency, decreased cortex ATP levels, and cognitive deficits have been found in mice lacking insulin-like growth factor 1 (IGF1)." (PMID 34959337, 2021).
diabetic angiopathy (1 paper, 2016). "The actions of GH are mediated by IGF-1, and the levels of both molecules have been correlated with the thickness of the capillary basement membrane as well as with diabetic angiopathy." (PMID 27213158, 2016).
diabetic foot ulcers (1 paper, 2013). "We believe that HBOT is effective in the treatment of diabetic foot ulcers, with an elevation of IGF-1." (PMID 23671876, 2013). "In the present study, we aimed to determine whether IGF-1 levels were changed in response to HBOT in diabetic foot ulcers." (PMID 23671876, 2013). "In the present study, we aimed to investigate alterations of IGF-1 after HBOT for diabetic foot ulcers to determine whether it could be a predictive factor of wound healing with HBOT." (PMID 23671876, 2013). "We also investigated whether IGF-1 was a predictive indicator of wound healing in diabetic foot ulcers treated with HBOT." (PMID 23671876, 2013).
diarrhoea (1 paper, 2023). "A previous study reported the correlation between diarrhoea due to enteric infections, IGF-1 concentration, systemic inflammation biomarker, and linear growth impairment in stunted children aged 6 to 24 months from Brazil." (PMID 37946290, 2023).
Dravet syndrome (1 paper, 2021). "In patients with Dravet syndrome, short stature and low levels of insulin-like growth factor 1 (IGF-1) were found." (PMID 34281215, 2021).
EBV infection (1 paper, 2021). "They documented that EBV infection induced the expression of IGF-1 via small components called EBV-encoded small RNAs (EBERs)." (PMID 34452353, 2021).
endometrial adenocarcinoma (1 paper, 2021). "IGF1 was also shown to mediate the functional role of FTO in endometrial adenocarcinoma." (PMID 34149936, 2021). "In our results, IGF1 and IRS1, essential factors in the glucose metabolism, thermogenesis, and glucose catabolic process 30, were considered as the potential target genes of FTO in the regulation of endometrial adenocarcinoma." (PMID 34149936, 2021).
enteritis (1 paper, 2010). Inflammation of the small intestine. "IGF-1 is a potent stimulator of intestinal crypt cellular growth, and has been used as a therapeutic approach to facilitate the intestinal repair process in gastrointestinal disorders, such as enteritis and IBD." (PMID 20886090, 2010).
epileptic encephalopathies (1 paper, 2025). "Similarly, novel pharmacological agents such as NMDA receptor antagonists for GRIN2A/GRIN2B mutations, KCNQ channel openers for KCNQ2-related epileptic encephalopathies, and IGF-1 analogues for trophic deficiency syndromes signify the forthcoming generation of personalized treatments." (PMID 41470225, 2025).
Epileptic spasm (1 paper, 2024). A sudden flexion, extension, or mixed extension-flexion of predominantly proximal and truncal muscles that is usually more sustained than a myoclonic movement but not as sustained as a tonic seizure. "In the TTX brain injury model of epileptic spasms, we undertook experiments to evaluate the impact of IGF-1 deficiencies on neocortical interneurons and their role in spasms." (PMID 39516073, 2024).
Escobar Syndrome (1 paper, 2022). "This makes IGF-1 an interesting biomarker in investigating Escobar syndrome." (PMID 36292632, 2022).
facial nerve palsy (1 paper, 2020). "Our objective herein is to demonstrate that IGF-1 shows promise as a regenerative medical treatment protocol for intractable peripheral facial nerve palsy caused by Bell’s palsy or Ramsay Hunt syndrome and that IGF-1 receptors are present in the facial nerve." (PMID 32513097, 2020). "Our results showed, as described herein, that IGF-1 is a promising substance and should be further studied as a treatment option for peripheral facial nerve palsy patients diagnosed with Bell’s palsy or Ramsay Hunt syndrome." (PMID 32513097, 2020). "IGF-1 is a small peptide (7.5 kDa) naturally produced mainly in the liver, with lower levels within the brain and peripheral nerves which is significant for facial nerve palsy." (PMID 32513097, 2020).
facial paralysis (1 paper, 2023). Severe or complete loss of facial muscle motor function. "Studies have shown that IGF-1 injections can reinnervate paralyzed muscles in experimental models of facial paralysis." (PMID 37505732, 2023).
food allergy (1 paper, 2024). Gastrointestinal disturbances, skin eruptions, or shock due to allergic reactions to allergens in food. "Some studies have reported that SCFAs maintain mesenteric lymph node insulin‐like growth factor 1 (IGF‐1) levels, which inhibit Th2 cell differentiation, thereby alleviating dysbiosis‐induced food allergy." (PMID 39619969, 2024).
gangrene (1 paper, 2025). Death of tissue, usually in considerable mass and generally associated with loss of vascular (nutritive) supply and followed by bacterial invasion and putrefaction. "Through a systematic analysis of 12 drugs and six key genes (IGF1, IL17A, ACE, FGF2, IL6 and TLR4), we have provided a new scientific perspective on gangrene prevention in diabetic patients." (PMID 40657379, 2025).
geographic atrophy (1 paper, 2023).
giant cell tumor (1 paper, 2018). A benign, intermediate, or malignant tumor that arises from the bone or soft tissue. "In this study, the aim is to verify, by immunohistochemistry, the expression of IGF1, MDM2, STAT1, and RAC1 and investigate their potential relationship with GCT recurrence, in a large cohort of patients with a giant cell tumor of the bone." (PMID 29651441, 2018).
giant cell tumor of bone (1 paper, 2018). "In our previous study, mouse double minute 2 homolog (MDM2), insulin-like growth factor 1 (IGF1), signal transducer and activator of transcription 1 (STAT1), and Rac family small GTPase 1 (RAC1) were correlated with the recurrence of giant cell tumor of bone (GCT)." (PMID 29651441, 2018).
Gliosis (1 paper, 2022). Gliosis is the focal proliferation of glial cells in the central nervous system. "At 2 years of age, there is a high degree of eye-to-eye variability, but even so, IGF-1 KD eyes had a higher median gliosis score than age-matched controls, and 3/9 IGF-1 KD eyes exhibited a high degree of gliosis (score 3 or higher) compared to 0/7 control eyes." (PMID 35356301, 2022).
Hashimoto thyroiditis (1 paper, 2024). An autoimmune disorder caused by the production of autoantibodies against thyroid tissue. "Many thyroid growthstimulatingfactors, such as TSH, insulin-like growth factor-1, and fibroblast growth factor, mightbe involvedin the development of adenomatous lesions in patients with Hashimoto’s thyroiditis." (PMID 39224552, 2024).
HELLP syndrome (1 paper, 2023). A life-threatening condition that can potentially complicate pregnancy. "Correlation analysis was used to observe the correlation between IGFBP-3 and IGF-1/TGF-β1/VEGF in maternal and umbilical blood, as well as that between maternal serum IGFBP-3 and clinical diagnostic indicators of HELLP syndrome." (PMID 37950229, 2023). "In this study, we found that IGF-1 levels in the maternal and umbilical blood of patients with HELLP syndrome were lower than those of healthy pregnant women." (PMID 37950229, 2023). "The expression of IGFBP-3 is elevated in HELLP syndrome, which may subsequently promote cell apoptosis by affecting the expression and function of IGF-1, VEGF, and TGFβ1 in the IGF/PI3K/Akt, TGF-β1/Smad3, and VEGF/eNOS/NO pathways." (PMID 37950229, 2023).
Hemophagocytosis (1 paper, 2024). Phagocytosis by macrophages of erythrocytes, leukocytes, platelets, and their precursors in bone marrow and other tissues. "Pinho et al26 observed a positive association between low expression of insulin-like growth factor-1 (IGF-1) and lower hemoglobin levels in patients with severe VL, suggesting a pathogenic mechanism different from that related to cytokine production and hemophagocytosis." (PMID 38422344, 2024).
Hepatosplenomegaly (1 paper, 2010). Simultaneous enlargement of the liver and spleen. "However, it remains to be determined whether or not there is an association between IGF-1 levels and childhood hepatosplenomegaly in the absence of periportal fibrosis." (PMID 19818465, 2010).
Hereditary breast cancer (1 paper, 2013). Breast carcinoma that has developed in relatives of patients with history of breast carcinoma.
hereditary cancer syndromes (1 paper, 2025). "Such a synergistic action offers a promising method for managing inflammation and IGF-1 signalling in patients with hereditary cancer syndromes." (PMID 41335382, 2025).
HIV-1 infection (1 paper, 2019). The type species of lentivirus and the etiologic agent of acquired immunodeficiency syndrome (AIDS). "While a limitation of the study were the small number of cases, the study demonstrates that maternal HIV-1 infection might not have a dramatic influence on placental IGF1, IGFBP1, MMP2, MMP9, ANG1, ANG2 and Gal-13 levels in Cameroonian pregnant normotensive women with majority receiving cART." (PMID 31042729, 2019).
HIV-associated neurocognitive disorder (1 paper, 2015). HIV-associated neurocognitive disorder (HAND) remains a common complication of HIV infection in the combination antiretroviral therapy (ART) era. "We also determined whether IGF1 or IGF2 deficiency is associated with HIV-associated neurocognitive disorder (HAND) and whether the levels of soluble IGF2R (an IGF scavenging receptor, which we also have found to be a cofactor for HIV infection in vitro) correlate with HIV viral load (VL)." (PMID 25890304, 2015).
human papillomavirus infection (1 paper, 2024). "The TNF, VEGFA, JUN, and IGF-1 genes and neuron death, PI3K-Akt, and human papillomavirus infection signalling pathways may possibly explain this association." (PMID 38977982, 2024). "The TNF, VEGFA, JUN, and IGF-1 genes and the neuron death, PI3K-Akt, and human papillomavirus infection signalling pathways may possibly explain this association." (PMID 38977982, 2024).
hypercementosis (1 paper, 2020). A regressive change of teeth characterized by excessive development of secondary cementum on the tooth surface. "Further, a direct role of IGF-1 excess would affect all the teeth equally, leading to diffuse hypercementosis visible on X-ray examinations." (PMID 32738132, 2020).
hypermobility syndrome (1 paper, 2011). "In patients with hypermobility syndrome (including several cases of DDH), growth hormone, insulin, and IGF-1 levels were elevated, leading us to endocrine abnormalities in DDH." (PMID 24977057, 2011).
hyperopia (1 paper, 2011). A refractive error in which rays of light entering the eye parallel to the optic axis are brought to a focus behind the retina, as a result of the eyeball being too short from front to back. "Low IGF-1 serum concentrations were associated with hyperopia in these studies." (PMID 21655358, 2011).
hypophosphatemic rickets (1 paper, 2011). Rickets due to low serum phosphate concentrations, the cause of which can be nutritional or genetic. "The acceleration in growth velocity could be attributed to the increased concentration of circulating IGF-1, the increase in efficiency of food utilization with rhGH, and the conventional therapy for hypophosphatemic rickets." (PMID 21859490, 2011).
intestinal infection (1 paper, 2019). "Another murine intestinal infection model induced by Citrobacter rodentium suggested that linear growth failure was associated with systemic inflammation and suppressed serum levels of IGF-1." (PMID 31221091, 2019).
intestinal obstruction (1 paper, 2017). Blockage of the normal flow of the intestinal contents within the bowel. "The results from this study indicate that decreased IGF-1 levels are highly correlated with growth in CF mice, independent of CF intestinal obstruction." (PMID 28384265, 2017).
intrahepatic cholangiocarcinoma (1 paper, 2025). A carcinoma that arises from the intrahepatic bile duct epithelium in any site of the intrahepatic biliary tree. "Human intrahepatic cholangiocarcinoma expresses IGF‐1 and IGF‐1 receptors, which act synergistically in regulating cell growth and apoptosis." (PMID 40304434, 2025). "IGF‐1 and IGF‐1R were expressed in all intrahepatic cholangiocarcinoma biopsies." (PMID 40304434, 2025).